ABCA1 (ATP binding cassette subfamily A member 1)
Diseases named in the same sentence as ABCA1 in open-access papers (continued):
Sharing a sentence is not in itself a finding about the gene and the disease.
atherosclerosis (continued). "In cases where mouse peritoneal macrophages were loaded with high cholesterol, ABCA1 and ABCG1 expression was enhanced while combined deficiency of both receptors resulted in foam cells accumulation and atherosclerosis." (PMID 29113088, 2017). "The potential of cathepsin B, S, and K to influence ABCA1 protein level regulation further supports the concept for their implication in atherosclerosis." (PMID 28919859, 2017). "Phospho-AKT modulates PPARγ/LXR driven gene expression of which ABCA1 is a prominent target with well-documented roles in lipid metabolism and atherosclerosis." (PMID 29144234, 2017). "In hyperlipidemic mice, deletion of ACAT1 results in both impairment of ABCA1 dependent cholesterol efflux and elevated atherosclerosis." (PMID 28662670, 2017). "In support, recruitment of Dnmt1 by Ezh2 at the ABCA1 promoter is shown to transcriptionally silence ABCA1 expression, and accelerate progression of atherosclerosis." (PMID 29261844, 2017). "It is well known that monocyte-derived macrophages are the main factors in the development of atherosclerosis, and ATP-binding cassette transporter A1 (ABCA1) is highly expressed in macrophages." (PMID 27295295, 2016). "Taken together, our data suggest that EZH2 is involved in the regulation of lipid accumulation and atherosclerosis development by inhibiting ABCA1-mediated cholesterol efflux." (PMID 27295295, 2016). "Conversely, EZH2 overexpression stimulated DNMT1-induced ABCA1 gene promoter methylation and atherosclerosis." (PMID 27295295, 2016). "Studies show that the activation of LXRα, one of the LXRs, attenuates the atherosclerosis formation by an increase in expression of cholesterol efflux transporters ABCA1 and ABCG1 in macrophages, and excretion transporters ABCG5 and ABCG8 in enterocytes." (PMID 27399689, 2016). "EZH2-induced downregulation of ABCA1 gene expression promotes foam cell formation and the development of atherosclerosis by DNA methylation of ABCA1 gene promoter." (PMID 27295295, 2016). "For this reason, current therapeutic perspectives in atherosclerosis aim at promoting cholesterol efflux by a process resulting in an increase in ABCA1 and ABCG1 expression that generates higher amount of HDL." (PMID 27252658, 2016). "ABCA1 mutations cause a severe HDL deficiency syndrome, cholesterol accumulation in tissue macrophages and atherosclerosis in Tangier disease." (PMID 26986486, 2016). "ABC transporters are particularly relevant for macrophages, since combined deficiency of ABCA1 and ABCG1 promotes foam cells accumulation and accelerates atherosclerosis, and also impairs macrophage migration." (PMID 27545843, 2016). "Transgenic mice that express a high level of ABCA1 present an increase in cholesterol efflux in macrophages and exhibit a low incidence of developing atherosclerosis." (PMID 27396856, 2016). "The function of ABCA1 is to mediate apolipoprotein A-I (apoA-I)-dependent cholesterol efflux, which has been identified as an important target in the treatment of atherosclerosis." (PMID 27295295, 2016). "Mutations of the ABCA1 gene cause a decrease in the levels of HDL cholesterol, with a consequent increase in atherosclerosis." (PMID 25875942, 2015). "Reduced cholesterol efflux is the consequence of lacking ABCA1 expression in vitro; it can lead to increase in atherosclerosis, but upregulation of ABCA1 results in reduction of atherosclerosis." (PMID 26788366, 2015).
atherosclerosis (continued). "The fundamental role of ABCA1 in the formation of foam cells and atherosclerosis has already been established: it mediates the active transport of intracellular cholesterol and phospholipids to apolipoprotein AI, which is the main lipoprotein of the HDL." (PMID 25875942, 2015). "It was suggested that ABCA1 protects against atherosclerosis by removing cholesterol from macrophages in the artery wall and therefore prevents the formation of foam cells, which are critical for the formation of atherosclerotic plaque." (PMID 25958224, 2015). "The findings support the feasibility of ABCA1 as a safe and efficient target for the treatment of atherosclerosis conditions." (PMID 26207756, 2015). "We found that ABCA1 protein expression was significantly increased in the rosiglitazone group, compared with the atherosclerosis group." (PMID 25604880, 2015). "Immunohistochemical staining revealed substantial ABCA1 and SR-B1 protein expression in the aortic plaques in both the atherosclerosis and rosiglitazone groups." (PMID 25604880, 2015). "Many studies have proven that defects in ABCA1 impaired apoA-1-mediated intercellular lipid efflux in early atherosclerosis." (PMID 25601961, 2015). "At the end of the 12-week experimental period, ABCA1 protein and mRNA expression in the peritoneal macrophages and hepatocytes was significantly lower in the atherosclerosis group compared with the control group (P<0.05)." (PMID 25604880, 2015). "Macrophage ABCA1 is an important factor that regulates intracellular lipid homeostasis in macrophages and thus prevents atherosclerosis." (PMID 26110874, 2015). "Compared with the atherosclerosis group, the rosiglitazone group had a significantly higher level of ABCA1 expression in the peritoneal macrophages and hepatocytes at both the mRNA and protein level (P<0.01)." (PMID 25604880, 2015). "Macrophages play a central role in atherosclerosis, and ABCA1 is critical for cellular cholesterol efflux." (PMID 24733347, 2014). "Mutations in the ABCA1 gene result in Tangier disease, a rare inherited disorder characterized by severe reduction in the amount of HDL and increased risk of atherosclerosis." (PMID 24733347, 2014). "Numerous epidemiological studies have evaluated the associations between ATP-binding cassette transporter 1 (ABCA1) R219K (rs2230806) and M883I (rs4149313) polymorphisms and atherosclerosis (AS), but results remain controversial." (PMID 24466114, 2014). "ABCA1 plays an important role in reverse cholesterol transport; its activity is associated with HDL cholesterol concentration and atherosclerosis." (PMID 25145866, 2014). "Third, apoA-I promotes reverse cholesterol transport through the macrophage ABCA1 and protects large vessels from atherosclerosis, which has been related to WMLs in several studies." (PMID 24820970, 2014). "ATP-binding cassette transporter A1 (ABCA1) is critical in exporting cholesterol from macrophages and plays a protective role in the development of atherosclerosis." (PMID 24086374, 2013). "As increased ABCA1 expression and decreased NF-kB activity can reduce atherosclerotic lesion sizes, we measured the effects of BA on the development of atherosclerosis in apoE−/− mice." (PMID 24086374, 2013). "Over expression of ABCA1 of murine bone marrow in normal mice were transplanted and the injury degree in atherosclerosis decreased." (PMID 24170990, 2013). "In normal mice transplanted into ABCA1 knockout mice bone marrow, the mice atherosclerosis injury increased significantly." (PMID 24170990, 2013).
atherosclerosis (continued). "Macrophage-specific deletion of ABCA1 results in an increase in atherosclerosis, whereas overexpression of ABCA1 in macrophages provides protection from atherosclerosis." (PMID 24086374, 2013). "In the liver, ABCA1 is implicated in control of HDL synthesis, which represents another means of protecting against atherosclerosis." (PMID 22919365, 2012). "We found that ABCA1 and SR-BI protein positive area were significantly higher in probucol group than in atherosclerosis group." (PMID 22078494, 2011). "Given the association between ABCA1 mutation and atherosclerosis as well as the observance of ABCA1 downregulation in atherogenesis, support is given to the notion that the dysregulation of ABCA1 facilitates the development of atherosclerosis." (PMID 21490773, 2011). "ABCA1 protects against atherosclerosis by facilitating cholesterol efflux from macrophage foam cells in the arterial wall to extracellular apolipoprotein (apo) A-I." (PMID 22022523, 2011). "This suggests that in the progression of atherosclerosis, posttranscriptional processes prevent the formation of ABCA1." (PMID 21490773, 2011). "The results showed that ABCA1 and SR-BI protein expressions in probucol group both in hepatocytes and peritoneal macrophages were higher than in atherosclerosis group." (PMID 22078494, 2011). "Although the functions of macrophage ABCA1 and apoE in the development of atherosclerosis have been studied extensively, their potential combined role in atherosclerotic lesion development is still unexplored." (PMID 22022523, 2011). "On the contrary, acetyl salicylic acid induced the expressions of ABCA1 and SR-BI, two molecules known to reduce the progression of atherosclerosis, at both mRNA and protein levels." (PMID 20137092, 2010). "Although LRP1 and ABCA1 therefore both play import ant and distinct roles in cellular cholesterol homeostasis and atherosclerosis, the functional interaction between these two membrane proteins has never been investigated." (PMID 19718435, 2009). "Homozygous mutations including deletions and polymorphisms of the ATP-binding cassette transporter 1 (ABCA1) cause Tangier disease, a rare autosomal recessive disorder with congenital HDL deficiency and increased risk of atherosclerosis." (PMID 17553166, 2007). "Mutations in ABCA1 cause Tangier disease, which is associated with low HDL cholesterol and accelerated atherosclerosis." (PMID 17132070, 2006). "Among the ABC transporters, ABCG1 and ABCA1 are well-known for their roles in cholesterol efflux, which is essential for maintaining lipid homeostasis and preventing the formation of lipid-laden macrophages in atherosclerosis." (PMID 41252867, 2025). "Listerin regulates the progression of atherosclerosis through ABCA1." (PMID 40526435, 2025). "In atherosclerosis, it enhances cholesterol efflux via the circTTP2/miR‐3073b‐5p/ABCA1 axis." (PMID 40796179, 2025). "Additionally, FXR activation downregulates the expression of CD36 and ABCA1 in macrophages, leading to decreased cholesterol uptake, thus preventing atherosclerosis." (PMID 40076864, 2025). "Nanotherapy targeting macrophage Listerin may be a meaningful therapeutic strategy for ameliorating atherosclerosis by activating the macrophage cholesterol efflux receptor ABCA1." (PMID 40526435, 2025). "In cell experiments, homocysteine (Hcy), an independent risk factor for atherosclerosis, was shown to inhibit the LXRα–ABCA1 lipid metabolism pathway in THP-1-derived foam cells by downregulating LXRα, ABCA1, and ABCG1 expression, thereby promoting foam cell formation." (PMID 41425976, 2025). "ABCA1, on the other hand, facilitates cholesterol efflux to HDL, reducing atherosclerosis risk." (PMID 40699832, 2025).
atherosclerosis (continued). "Dietary or metabolic factors which modulate ABCA1 activity might possess a profound lead on cholesterol transport and atherosclerosis." (PMID 38755663, 2024). "Similarly, 12-Hydroxyeicosapentaenoic acid reduces foam cell formation and atherosclerosis via activation of PPARγ–ABCA1/ABCG1 signaling pathways." (PMID 38699583, 2024). "Our results revealed downregulated transcripts of inflammatory cytokines affected by LZ8, including ABCA1, which suggests that cholesterol efflux might also be impaired in the progression of atherosclerosis." (PMID 39457059, 2024). "From these findings, we conclude that inhibiting miR-33a-5p in MLC may protect against atherosclerosis by promoting ABCA1-dependent cholesterol efflux." (PMID 38535619, 2024). "Antagomir-mediated inhibition of miR-33a-5p, a microRNA that represses ABCA1 translation, promotes ABCA1-dependent cholesterol efflux and may impede atherosclerosis development." (PMID 39765632, 2024). "In turn, ABCA1 knockout in mice translated into enhanced atherosclerosis compared to control mice." (PMID 39273193, 2024). "Additionally, overexpression of ABCA1 in mouse liver also increases hepatic and plasma cholesterol, which can promote atherosclerosis." (PMID 39765632, 2024). "Hence, ABCA1 expression is considered to be atheroprotective, and studies that have involved assessing atherosclerosis in the context of ABCA1 manipulation support this notion." (PMID 37359759, 2023). "Furthermore, bone marrow cells from MeXis-deficient mice exhibited altered chromosome architecture at the Abca1 locus, impaired cholesterol efflux, and accelerated atherosclerosis development." (PMID 37509544, 2023). "The membrane transporters ABCA1 and ABCG1 are involved in the reverse transport of cholesterol and stimulate the HDL synthesis in hepatocytes, therefore the deficiency of these transporters promotes the acceleration of atherosclerosis." (PMID 37754229, 2023). "Astaxanthin also suppressed foam cell formation and atherosclerosis development by enhancing ABCA1, ABCG1, and SR-B1 expression in apoE-/- mice 133, 134, suggesting that circUGGT2 may be an anti-atherosclerotic RNA in vivo." (PMID 37324939, 2023). "Cholesterol levels may be also reduced by Hsp25 immunotherapy, Hsp25 reduces plaque cholesterol by 30% and prevents experimental atherosclerosis in mice, which requires GM-CSF-regulated ABCA1 and ABCG1 expression." (PMID 37077734, 2023). "The ABCA1 and ABCG1 membrane transporters participate in cholesterol transport outside of any cell type and favor the increase in HDL synthesis in hepatocytes, therefore a deficiency of these transporters promotes accelerated atherosclerosis." (PMID 37754229, 2023). "The upregulation of the ABCA1 expression pathway by functional nutrients may provide research targets for the prevention and treatment of atherosclerosis." (PMID 36904298, 2023). "Indeed, compared with WT mice, miR-33b KI mice have lower HDL-C levels and more severe atherosclerosis or aortic aneurysm formation resulting from the reduced expression of the cholesterol transporter ABCA1." (PMID 37263777, 2023). "Atherosclerosis may be successfully treated by increasing cholesterol efflux through ATP-binding cassette transporter A1 (ABCA1)-mediated active transfer from macrophages to extracellular space." (PMID 38001931, 2023). "ABCA1 is a key protein in the reverse cholesterol transport process, which can promote macrophages’ excretion of lipids, thereby inhibiting the development of atherosclerosis." (PMID 37670950, 2023). "MiR-144 binds to the 3'UTR region site of ABCA1/G1.This will reduce the outflow of cholesterol to apolipoprotein A1 (ApoA1) mediated by the ABCA1/G1 of hepatocytes and macrophages, promoting inflammatory activation and atherosclerosis." (PMID 37189131, 2023).
atherosclerosis (continued). "Studies have shown that they are over-regulated in atherosclerosis and negatively related to plasma cholesterol and ATP-binding cassette transporter A1 (ABCA1) levels, representing a new biomarker for clinical diagnosis and treatment of coronary atherosclerosis." (PMID 37958528, 2023). "Moreover, IL-4/6 and NF-κB can also downregulate the expression of ABCA1 in macrophages and promote the development of atherosclerosis." (PMID 37670950, 2023). "A single deficiency of ABCA1 or ABCG1 in macrophages has been reported to not increase atherosclerosis, probably because ABCA1 deficiency leads to upregulation of ABCG1 expression." (PMID 36904298, 2023). "In atherosclerosis, it has been reported that miR-34a modulates ATP binding cassette subfamily A member 1 (ABCA1) expression in macrophages, which could have direct effects on cholesterol efflux and reverse cholesterol transport in these cells." (PMID 37275892, 2023). "Moreover, combined deficiency of ABCA1 and ABCG1 promotes foam cell accumulation and accelerates atherosclerosis in mice." (PMID 36713845, 2023). "ABCA1 is an important subject for studies on the pathogenesis of atherosclerosis." (PMID 36363640, 2022). "Mice deficient in ABCA1 and ABCG1 display leukocytosis, increased proliferation of hematopoietic stem and multipotential progenitor cells in the bone marrow, and accelerated atherosclerosis." (PMID 35052806, 2022). "Therefore, ABCA1 plays an important function in the development of atherosclerosis and hypertension." (PMID 35669754, 2022). "Genetic disruption of SphK2 in mouse models has been reported to exacerbate atherosclerosis, thus epigenetic regulation of ABCA1 and LXR target genes by SphK2 may be the key to understanding the anti-atherogenic mechanism of FTY720." (PMID 36498944, 2022). "ABCA1 has been shown to be causally involved in reverse cholesterol transport, and combined deletion of ABCA1 and ABCG1 in mouse macrophages dramatically impaired cholesterol efflux to ApoA-I, accelerated atherosclerosis, and promoted foam cell accumulation." (PMID 36077004, 2022). "Moreover, atherosclerosis in ABCA1 transgenic and knockout mouse models was reported to increase significantly." (PMID 35743794, 2022). "Similarly HIFα/β also binds to the promoter region of several lipid related genes including ABCA1 in response to hypoxia, which, in turn, activates cholesterol efflux and prevents lipid overload and foam cells, hallmarks of atherosclerosis." (PMID 36407436, 2022). "Deacetylation of PPARγ inhibits the cholesterol efflux PPARγ/LXRα/ABCA1 pathway, increased production of proinflammatory M1 macrophages and promotes the development of inflammatory response, leading to the onset and development of atherosclerosis." (PMID 35309069, 2022). "According to previous studies, ABCA1 has a protective effect against atherosclerosis." (PMID 35743794, 2022). "However, the effect of ABCA1 on cardiovascular risks and atherosclerosis development is controversial." (PMID 35498045, 2022). "ABCA1 mutations are associated with the development of Tangier disease, which is characterized by a significant decrease in HDL levels, which corresponds to premature atherosclerosis." (PMID 36363640, 2022). "Similarly, mice deficient in ABCA1 and ABCG1 specifically in endothelial cells demonstrate decreased eNOS activity, increased endothelial inflammation, and accelerated atherosclerosis." (PMID 35052806, 2022). "This may provide a novel potential therapeutic target for increasing ABCA1 activity to reduce foam cell formation and prevent atherosclerosis development." (PMID 35743794, 2022). "Thus, asprosin suppresses macrophage lipid accumulation and mitigates atherosclerosis by promoting ABCA1- and ABCG1-dependent cholesterol efflux." (PMID 35902881, 2022).